NLGN3 (neuroligin 3)
Diseases named in the same sentence as NLGN3 in open-access papers (continued):
Sharing a sentence is not in itself a finding about the gene and the disease.
glioma (continued). "NLGN3 promotes tumour growth and feedforwards its own expression in glioma cells, through induction of the PI3K-mTOR pathway activity." (PMID 38834748, 2024). "While NLGN3 also possesses the capability to stimulate synapse formation between neurons and gliomas, its proliferative effect on pediatric cortical high‐grade gliomas (pHGGs) is relatively less pronounced compared to BDNF." (PMID 39469896, 2024). "Neuron-OPCs synapses are retained in glioma, and neuronal activity drives glioma proliferation through a paracrine mediator, such as neuroligin-3 from neurons." (PMID 39258226, 2024). "A vital mechanism that orchestrates the neural regulation of brain cancer is the activity‐dependent cleavage and secretion of NLGN3, which promotes glioma proliferation through multiple signaling pathways." (PMID 39469896, 2024). "As a postsynaptic adhesion molecule, NLGN3 itself is also highly expressed in glioma cells, and previous studies have reported that NLGN3 can promote glioma progression." (PMID 38254206, 2024). "Paracrine signaling is the neuronal activity that propels tumor progression, in the context of gliomas, via neuroligin-3 and BDNF, as well as through neuron-glioma synapses mediated by AMPA receptors, synapses which are modulated by BDNF." (PMID 38534769, 2024). "The MAPK and AKT-mTOR pathways have been demonstrated to promote the formation of gliomas when activated by NLGN3." (PMID 38720772, 2024). "Monocyte-produced metalloprotease (MMP) ADAM10 causes the release of soluble synaptic protein NLGN3, which, through the PI3K/mTOR pathway, induces glioma growth." (PMID 38193532, 2024). "Accordingly, NLGN3 expression is inversely correlated with overall survival and conditions the growth of many subtypes of pediatric and adult gliomas." (PMID 38834748, 2024). "Neurons can also release the mitogen neuroligin‐3 (NLGN3) and promote the glioma cell proliferation via the PI3K‐mTOR signaling pathway, which is related to survival in patients with high‐grade glioma." (PMID 36464889, 2023). "Specifically, the mediation of NLGN3-induced signaling by Gαi1/3 is crucial for neuronal-driven glioma growth." (PMID 37511496, 2023). "In the last 5 years, a large series of papers have been focused on NLGN3 as a key driver of glioma progression." (PMID 37511496, 2023). "One of the top candidates is the synaptic ligand NLGN3, which has also been described to facilitate neuron-glioma crosstalk and enhances tumor growth once released following neuronal activity." (PMID 38596241, 2023). "For example, Venkatesh and colleagues showed that neurally secreted NLGN3 invades the microenvironment of tumours and induces NLGN3 expression in glioma cells to promote tumour growth." (PMID 37509099, 2023). "NLGN3 was shown to induce expression of synaptic genes required for neuron-glioma synapse formation." (PMID 37880221, 2023). "Inhibition of ADAM10, the enzyme responsible for NLGN3 cleavage, was shown to reduce glioma growth in mouse models of glioblastoma." (PMID 36614191, 2023). "In neurons, NLGN3 is secreted by enzymatic cleavage of the N-terminal ectodomain, and this secreted form acts as a mitogen to neighboring glioma cells." (PMID 37443071, 2023). "A fused brain organoid glioma model was used to study tumor-neuron interactions and confirmed the reduction of tumor invasion by NLGN3 inhibitors." (PMID 38596241, 2023). "Signaling molecules released by neurons, such as the synaptic protein neuroligin-3 (NLGN3), can influence glioma progression by activation of the PI3K/mTOR pathway." (PMID 36647827, 2023). "It should be highlighted that the effects of NLGN3 appeared to be similar across different histologic and molecular subtypes of glioma, at least in these models." (PMID 36968288, 2023). "The knockout of NLGN3 (an NGS gene) can decrease the invasion of glioma in vivo in mouse models, supporting that NGS genes can be therapeutic targets." (PMID 37693314, 2023).
glioma (continued). "Among these mitogens, the synaptic protein neuroligin-3 (NLGN3) was identified as the primary candidate, and soluble NLGN3 was shown to be necessary and sufficient for the robust proliferation of high-grade glioma cells." (PMID 37511496, 2023). "Although no previous studies were found to correlate its expression to breast cancer metastasis, NLGN3 was shown to advocate the growth of high-grade glioma." (PMID 37175499, 2023). "A very recent study of our group has also shown Gαi1/3 are key proteins mediating NLGN3-induced signaling in glioma cells." (PMID 37880221, 2023). "NLGN3, a protein normally on the neuron surface, can be secreted as a mitogen and promote the growth and infiltration of glioma cells through the PI3K-mTOR pathway." (PMID 37693314, 2023). "The protease ADAM10 (a disintegrin and Metalloprotease 10) is stimulated by neuronal activity to promote NLGN3 extracellular domain shedding into the tumor microenvironment, which promotes glioma growth." (PMID 36499024, 2022). "Neuroligin-3 stimulates many carcinogenic pathways, not only upregulating synapse-related genes, enabling neurons to communicate synaptically with gliomas to promote glioma growth, but also promoting GBM proliferation by activating PI3K as a mitogen." (PMID 36497459, 2022). "After cleavage by the metalloproteinase ADAM10, soluble NLGN-3 (sNLGN-3) binds on glioma cells leading to PI3K-mTOR signaling activation." (PMID 36357661, 2022). "One final comment on our data can be made concerning the role of neuroligin-3 (NLGN3) in glioma growth." (PMID 36056393, 2022). "Activity-dependent release of neuroliglin-3 (NLGN3) is required for GB progression in xenografts models, and NLGN3 induces the expression of synaptic proteins in glioma cells." (PMID 35877760, 2022). "Although the underlying mechanisms of Gαi1/3-mediated NLGN3 signaling and glioma cell progression need further characterization, the results of the present and previous studies 26 strongly indicate that Gαi1 and Gαi3 could be valuable therapeutic targets for treating human glioma." (PMID 34373757, 2021). "NLGN3 treatment promoted the growth of P1 primary glioma cells (with “scr-shRNA”), evidenced by increased EdU incorporation (at 48h) and cell number (at 72h)." (PMID 34373757, 2021). "NLGN3 was found to induce Gab1 activation, indicated by increased phosphorylation at Tyr-627 and Tyr-307 39 in P1 primary human glioma cells and U251MG cells." (PMID 34373757, 2021). "Significantly, shRNA-mediated stable knockdown of Gab1 inhibited NLGN3-induced Akt, Erk1/2 and S6K phosphorylation in U251 and primary glioma cells." (PMID 34373757, 2021). "Blocking the enzyme, ADAM10 that cleaves synaptic Nlgn3 is one therapeutic approach to disrupt this mechanism for glioma growth." (PMID 32542524, 2021). "Experiments in mouse glioma models suggest that the mechanism is based on the release of the ectodomain of a postsynaptic cell-adhesion molecule, neuroligin-3 (Nlgn3), which acts as a growth factor." (PMID 32542524, 2021). "Studies highlighted a crucial role of neuroligin-3 (NLGN3) in the mechanism of glioma progression 17-20." (PMID 34373757, 2021). "We concluded that possibly by mediating NLGN3-induced signaling transduction, Gαi1/3 are essential for glioma cell progression in vitro and in vivo." (PMID 34373757, 2021). "Blocking gliomas’ acquisition of neuron-derived NLGN3 can inhibit cancer growth that is regulated by neuronal activity." (PMID 34485271, 2021). "In conclusion, we proved that glioma-derived NLGN3 functions as a tumor promoter by upregulating AKT and Erk1/2 signaling pathways." (PMID 34485271, 2021). "Together, these results show that Gαi1 and Gαi3 are essential proteins for NLGN3 signaling in human glioma cells." (PMID 34373757, 2021). "Previous studies suggest that neuron-derived NLGN3 plays an important oncogenic role in the progression of glioma, which is consistent with our study." (PMID 34485271, 2021).
glioma (continued). "Then, we detected the NLGN3 expression in five human glioma cell lines, U87, U251, HS683, A172, and U373, using Western blot." (PMID 34485271, 2021). "NLGN3 resulted in upregulated Bcl-2 and downregulated Bax in glioma cells, which suggested that the mitochondrial-dependent apoptosis pathway was inhibited." (PMID 34485271, 2021). "In line with previous studies 18, 19, 40, NLGN3 mRNA levels were increased in human glioma tissues, and levels were higher in the late-stage gliomas." (PMID 34373757, 2021). "in xenograft glioma mouse models show that presynaptic and postsynaptic function is disrupted in the presence of glioma with microenvironmental neurolignin 3 (NLGN3) being hijacked to induce signaling through the PI3K/PTEN/AKT/mTOR pathway." (PMID 34532286, 2021). "The neuron derived synaptic adhesion molecular neuroligin-3 (NLGN3) plays an important role in glioma growth." (PMID 34485271, 2021). "In U251MG glioma cells, shRNA-mediated silencing of Gαi1/3 (“Gαi1/3 DshRNA”) similarly inhibited NLGN3-induced Akt and Erk1/2 phosphorylation." (PMID 34373757, 2021). "NLGN3 mediates synaptic communications between glioma cells and neurons through AMPA receptors and the glutamate signalling pathway." (PMID 33766119, 2021). "As Gab1-p85 association mediates PI3K-Akt activation and Gab1-SHP2 association is vital for Erk-MAPK cascade activation 39, we propose that Gab1 is a key adaptor protein for NLGN3 signaling in human glioma cells." (PMID 34373757, 2021). "Through the screening of activity-regulated secretion, they successfully identified the secreted NLGN3 as a leading protein that promotes the proliferation of glioma cells." (PMID 34485271, 2021). "TCGA cohorts showed that NLGN3 transcripts are higher in glioma tissues when compared to normal brain tissues, being significant in LGG tissues." (PMID 34373757, 2021). "Here in glioma cells, Gαi1/3 silencing, by targeted shRNAs, blocked NLGN3-induced RTKs endosomal translocation and subsequent Gab1 activation, without affecting RTK phosphorylation and expression." (PMID 34373757, 2021). "NLGN3 secreted from neurons was found to induce phosphorylation and activation of several key receptor tyrosine kinases (RTKs) on glioma cells to promote glioma progression 17-19." (PMID 34373757, 2021). "In our study, we first investigated the functions of glioma-derived NLGN3 in U251 and U87 cells by manipulating its expression." (PMID 34485271, 2021). "In control P1 glioma cells (expressing a scramble nonsense shRNA/“scr-shRNA”) NLGN3 potently induced phosphorylation of Akt, Erk1/2 and S6K, whereas signaling was almost blocked in P1 glioma cells transduced with Gαi1/3 DshRNA." (PMID 34373757, 2021). "NLGN3, a synaptic protein cleaved and secreted in an activity-dependent manner, was identified as the primary factor responsible for glioma progression 17-20." (PMID 34373757, 2021). "Recently, glutamatergic neurons have also been shown to regulate and advance glioma progression by secreting neuroligin-3 (NLGN3)." (PMID 33766119, 2021). "In the present research, we elucidated the functional effects of glioma-derived NLGN3 and discussed the feedback regulation pathway of LYN and NLGN3 in glioma cells to further improve our understanding of glioma progression." (PMID 34485271, 2021). "In the present research, we found that secreted NLGN3 in cell culture medium promoted the level of LYN phosphorylation in glioma cells." (PMID 34485271, 2021). "In glioma cells, NLGN3-induced cell growth, proliferation and migration were attenuated by Gαi1/3 depletion with shRNA, but facilitated with Gαi1/3 overexpression." (PMID 34373757, 2021). "In summary, in the glioma microenvironment, NLGN3 secreted by neurons and glioma cells activates LYN and upregulates ADAM10 expression, which can cleave NLGN3 to promote its secretion." (PMID 34485271, 2021).
glioma (continued). "Our current and previous results 26 have demonstrated that Gαi1 and Gαi3 levels are significantly upregulated in human glioma tissues, and their upregulation is correlated with poor patients survival, high tumor grade and NLGN3 upregulation." (PMID 34373757, 2021). "Our study demonstrates that glioma-derived NLGN3 promotes glioma progression by upregulating activity of LYN and ADAM10, which in turn promote NLGN3 cleavage to form a positive feedback loop." (PMID 34485271, 2021). "Recent studies have shown that ADAM10 is responsible for NLGN3 shedding from glioma cells, so we further studied the role of ADAM10 in this positive feedback loop." (PMID 34485271, 2021). "As neuron-secreted NLGN3 activates RTKs to promote glioma progression, we explored the potential function of Gαi1 and Gαi3 in NLGN3-induced signaling and glioma cell progression." (PMID 34373757, 2021). "To confirm the efficiency of the applied shRNA, we showed that Gαi1 and Gαi3 proteins were silenced in Gαi1/3 DshRNA-expressing P1 glioma cells (with NLGN3 treatment, at 72h)." (PMID 34373757, 2021). "Knockdown of endogenous NLGN3 significantly reduced the proliferation, migration, and invasion of glioma cells and down-regulated the activity of the PI3K-AKT, ERK1/2, and LYN signaling pathways." (PMID 34485271, 2021). "In the murine model, increased neuronal activity promotes the cleavage and secretion of NLGN3, which then triggers mitosis—and thereby tumor growth—in gliomas." (PMID 31953611, 2020). "Second, using optogenetic approaches, increased neuronal activity has been shown to drive high-grade glioma growth through the shedding of neuroligin-3, a protein normally involved in neuron–neuron communication." (PMID 32358581, 2020). "Mechanistically, NLGN3 can induce Fos expression, activate PI3K, Akt, and mTOR, and further induce NLGN3 expression in glioma cells." (PMID 33187183, 2020). "This glioma growth was found to be mediated by activity-dependent cleavage and secretion of the synaptic adhesion molecule neuroligin-3 from a postsynaptic neuron or oligodendrocyte precursor cell." (PMID 31884567, 2020). "The secreted soluble neuroligin-3 can act as a mitogen for the glioma, inducing focal adhesion kinase (FAK), phosphoinositide 3-kinase (PI3K)-mTOR pathway, expression of neuroligin-3 and other synapse genes, leading to the proliferation of the glioma cells." (PMID 31884567, 2020). "Subsequent investigations revealed that the induction of neuronal hyperactivity resulted in the release of secreted factors by neurons, such as BDNF or NLGN3, which support glioma progression and facilitate the synapsing of neurons onto glioma cells." (PMID 33187183, 2020). "Recently, the cleaved NLGN3 was detected in the medium from optogenetically stimulated acute cortical slices and reported to serve as the mitogen promoting glioma growth." (PMID 30056576, 2019). "More recently, it is shown that blocking the release of NLGN3 results in diminished tumor growth in animal models of high-grade glioma." (PMID 30094719, 2018). "Particularly, some studies have shown that neuronal cells in response to neuronal activity secrete portions (a cleavage product) of the protein synaptic adhesion molecule neuroligin-3 (NLGN3) that promotes glioma survival and proliferation." (PMID 30279357, 2018). "The investigators show that neuroligin-3 was both necessary and sufficient to lead to active high-grade glioma cell proliferation." (PMID 26120474, 2015). "Notably, in the context of high-grade gliomas and retinoblastomas, adjacent neurons and oligodendrocyte precursor cells secrete a protein identified as soluble neuroligin-3 (NLGN3)." (PMID 41601691, 2026). "Furthermore, the synaptic adhesion molecule NLGN3, another key paracrine factor, is critical for glioma progression." (PMID 40092993, 2025). "Among these, NLGN3 plays a pivotal role in high‐grade and low‐grade glioma proliferation." (PMID 40685688, 2025).
glioma (continued). "NLGN3 induces a synaptogenic gene expression profile in glioma cells, suggesting it may act as an upstream regulator of malignant synaptogenesis." (PMID 40685688, 2025). "In high-grade gliomas, soluble neuroligin-3 (NLGN3) secreted by neurons and oligodendrocyte precursor cells interacts with receptors on tumor cell surfaces, activating the PI3K-mTOR signaling pathway that governs cell proliferation and survival, thus facilitating tumor growth and metastasis." (PMID 40092993, 2025). "We hypothesized that shed NLGN3 subsequently triggers CSPG4 shedding from the membrane of glioma cells and OPCs in an autocrine and/or paracrine fashion." (PMID 40791371, 2025). "To directly assess this hypothesis, we treated in vitro cell cultures of glioma cells with recombinant NLGN3 ectodomain proteins for one hour, collected the conditioned medium, and performed western blot analysis using antibodies against the CSPG4 N-terminus." (PMID 40791371, 2025). "In previous studies, a similar phenomenon has been shown in glioma cells where neuronal activity-induced cleavage and secretion of transmembrane synaptic protein neuroligin-3 (NLGN3) to the extracellular space promoted proliferation of the neighboring glioma cells." (PMID 40678520, 2025). "However, the precise mechanisms mediating NLGN3 interactions with glioma surface signaling proteins remained elusive." (PMID 40791371, 2025). "Interestingly, the NF‐κB signaling pathway is activated in both NLGN3‐mediated effects and within the glioma network." (PMID 39469896, 2024). "Research has demonstrated that NLGN3 affects glioma cells and neurons in a paracrine manner." (PMID 38720772, 2024). "NLGN3 was necessary and sufficient to promote glioma cell growth." (PMID 38254206, 2024). "Studies have found that NLGN3 secreted by neurons can induce the phosphorylation and activation of several key receptor tyrosine kinases (RTKs) on glioma cells, including focal adhesion kinase activation upstream of PI3K–mTOR, thereby promoting glioma progression." (PMID 38254206, 2024). "Transcriptome sequencing demonstrated that KPNB1 could regulate the expression of NLGN3, which has been previously reported as a postsynaptic membrane protein that is highly expressed in the central nervous system and key to glioma progression." (PMID 38254206, 2024). "Specifically, in high‐grade gliomas such as adult glioblastoma, anaplastic oligodendroglioma, pediatric glioblastoma, and diffuse intrinsic pontine glioblastoma (DIPG), increased NLGN3 expression is associated with increased tumor aggressiveness and poorer patient survival." (PMID 39469896, 2024). "Moreover, they compared the effects of NLGN3 and BDNF on glioma, reporting that while NLGN3 upregulates the expression of AMPAR subunits, BDNF-TrKB signaling promotes AMPAR subunit trafficking to the glioma cell membrane." (PMID 38473812, 2024). "Notably, both brain‐derived neurotrophic factor (BDNF) and synaptic protein NLGN3 are instrumental in the proliferation of glioma through paracrine secretion in the TME." (PMID 39469896, 2024). "Studies have shown that NLGN3-induced phosphorylation of several key RTKs in glioma cells." (PMID 37880221, 2023). "In the TME, post-synaptic neurons support the progression of gliomas by promoting the transition of mitogenic to neoplastic cells through the upregulation of neuroligin-3 (NLGN3), inducing a phosphoinositide 3-kinase (PI3K) signaling-mediated proliferative activity in glioma cells." (PMID 37165457, 2023). "Given NLGN3 activates multiple pro-glioma molecular pathways, its reduction may disrupt crucial glioma signaling potential." (PMID 37345193, 2023). "In addition to synaptic functions, NLGN3 has oncogenic functions, which promote the proliferation of high-grade glioma." (PMID 37443071, 2023). "NLGN3 has been shown to have a paracrine influence on both neurons and glioma cells." (PMID 37345193, 2023). "Another neuroligin isoform (NLGN3) has been involved in glioma growth." (PMID 36499024, 2022).